PRPS1 (phosphoribosyl pyrophosphate synthetase 1)
Diseases named in the same sentence as PRPS1 in open-access papers (continued):
Sharing a sentence is not in itself a finding about the gene and the disease.
Hutchinson-Gilford progeria syndrome (1 paper, 2022). "In contrast, significant decrease in transcriptional level of PRPS1 was observed in human Hutchinson-Gilford progeria syndrome (HGPS)-derived fibroblast cell lines." (PMID 35742917, 2022).
lung adenocarcinoma (1 paper, 2025). A carcinoma that arises from the lung and is characterized by the presence of malignant glandular epithelial cells. "To assess the oncogenic potential of PRPS isoforms, we initially compared the mRNA levels of PRPS1 and PRPS2 in 47 cases of lung adenocarcinoma specimens with paired adjacent normal tissues." (PMID 40295500, 2025). "Our analysis revealed a significant upregulation of PRPS2 mRNA levels in 38 cases (81%) of lung adenocarcinoma compared to their adjacent normal tissues, while no significant alteration was observed for PRPS1 mRNA levels." (PMID 40295500, 2025). "In this study, we demonstrate that PRPS2, distinct from its highly inter-isoform conserved homolog PRPS1, promotes RNA m6A methylation in lung adenocarcinoma tumorigenesis through its canonical metabolic and non-metabolic functions." (PMID 40295500, 2025).
Sleep apnea (1 paper, 2025). An intermittent cessation of airflow at the mouth and nose during sleep is known as sleep apnea. "Though the gene with the highest loading on LV3, SRSF4, has not been previously associated with sleep apnea, the second and third highest loading genes, PIGT and PRPS1, were included in the HPO sleep apnea gene set." (PMID 40662804, 2025).
cancer (15 papers, 2010 to 2025). A tumor composed of atypical neoplastic, often pleomorphic cells that invade other tissues. "It is proposed that cancer cells gain resistance to thiopurine by acquiring hyperactivating PRPS1 mutations that bypass ADP- or GDP-dependent allosteric inhibition." (PMID 32650483, 2020). "Indeed, many diseases have been linked to PRPS1/2, including cancer." (PMID 27328773, 2016). "To assess physiological significance about PRPS1 O-GlcNAcylation, we investigated its impacts on cancer cell proliferation and growth." (PMID 37308732, 2024). "Although the ERK5 expression was unexpectedly not elevated in the tumor tissues, we observed that profound increase in ERK5 activated PRPS1/2 and enhanced the synthesis of nucleotides, and this is similar to most conditions in cancer." (PMID 36720864, 2023). "High expression of PRPS1/2 is a key driver for cancer stem cell high activity, including maintaining stem cell self-renewal, proliferation and even catalyzing tumorigenesis." (PMID 33493137, 2021). "More recently, studies have also discovered that PRPS1 and PRPS2 are mutated in therapy-resistant relapsed ALL cancer patients." (PMID 32650483, 2020). "Both NAD and nucleotides are essential for PRPS1 functions in cancer cell proliferation." (PMID 37308732, 2024). "Moreover, PRPS1 O-GlcNAcylation promoted tumorigenesis and affected cancer cell response to chemoradiotherapy." (PMID 37308732, 2024). "PRPS1 has also recently attracted attention for its role in the development of various cancers." (PMID 31443513, 2019). "Twenty-eight of 32 TCGA cancer types had increased expression of both JUN and PRPS1 in comparison with their respective normal tissues, indicating the importance of JUN and PRPS1 in tumorigenesis and tumor progression." (PMID 37909334, 2023). "Interestingly, PRPS1 may play different roles in different cancers." (PMID 31443513, 2019). "This was indeed the case, as the list of genes exclusively detected in cancer, including TRAF7, PRPS1, CDT1, and ZWINT, were previously reported as cancer marker genes." (PMID 20454660, 2010). "Previous studies have highlighted the role of c-Myc in upregulating PRPS2, but not its highly conserved inter-isoform homolog PRPS1, to meet the specific high demands for nucleotide synthesis in cancer cells." (PMID 40295500, 2025). "ACSL6, PRPS1 and PRPS2 genes represent potential therapeutic targets to limit cancer cell growth using specific inhibitors, which could re-program cancer cell metabolism by reducing FA." (PMID 31434359, 2019).
tumor (15 papers, 2018 to 2025). "In human tumor cells, Cdk1 promoted the phosphorylation of ribose-phosphate diphosphokinase 1 (PRPS1) at S103, and the loss of phosphorylation at S103 altered the cell cycle, which was similar to the alteration of the cell cycle observed in ΔBbTdp1 mutants." (PMID 34378960, 2021). "Interestingly, PRPS1 mRNA expression is associated with reduced survival and positively correlated with DNA replication, tumor proliferation, and the PI3K/AKT/mTOR signature in the TCGA data set, confirming its broad essential role in cell growth and proliferation." (PMID 37909334, 2023). "Overexpressed OGT substantially promoted tumor growth in vivo, with elevated PRPS1 O-GlcNAcylation and activity." (PMID 37308732, 2024). "The R196W mutant also inhibited cell proliferation and tumor cell growth in vivo and had much lower PRPS1 activity." (PMID 37308732, 2024). "In contrast, our animal experiments demonstrated that PRPS1 cell knockdown was significantly detrimental to tumor growth." (PMID 36203561, 2022). "We found that the protein expression of PRPS1 in the tumors was positively correlated with the tumor volume." (PMID 36203561, 2022). "qRT-PCR and Western blot analysis of PRPS1 expression in tumor tissues further revealed that PRPS1 expression levels in tumor tissues were consistent with cellular level results." (PMID 31443513, 2019). ", indicating that PRPS1 O-GlcNAcylation promotes tumor growth." (PMID 37308732, 2024). "Besides, the PRPP level and PRPP/R5P ratio were increased in tumors than in tumor-adjacent tissues, indicating that the activity of PRPS1/2 had increased." (PMID 36720864, 2023). "Importantly, further investigation revealed the phosphorylation at S41 of PRPS2 and at T225 of PRPS1 were all positively correlated with the expression of cell proliferation marker Ki67, confirmed their role in promoting tumor cell proliferation." (PMID 36720864, 2023). "To further confirm whether PRPS1 could promote tumor malignancy in vivo, we injected PRPS1-overexpressing or PRPS1-knockdown A875 cells and the corresponding control cells via the caudal vein to establish a metastatic tumor model in BALB/c nude mice." (PMID 36203561, 2022). "More importantly, PRPS1-overexpressing A875 cells significantly promoted tumor growth." (PMID 36203561, 2022). "In addition, we further compared the expression of PRPS1 in subcutaneous tumor tissues of nude mice by western blotting." (PMID 36203561, 2022). "PRPS1 may inhibit tumor cell proliferation and differentiation in addition to affecting cell migration." (PMID 31443513, 2019). "Moreover, PRPS1 knockdown substantially reduced tumor growth." (PMID 37308732, 2024). "In sum, our data illustrated the strong association between EGFR genomic alterations and increased expression of ERK5 which could phosphorylate the PRPS1/2, activated nuclear biosynthesis pathway, and in turn might promote tumor cell proliferation and impact prognosis." (PMID 36720864, 2023). "Glucose-triggered O-GlcNAcylation of phosphoribosyl pyrophosphate synthetase 1 (PRPS1) boosts generation of nucleotide and nicotinamide adenine dinucleotide (NAD) crucial for tumor growth." (PMID 40416363, 2025). "Here we demonstrated that glucose-induced PRPS1 O-GlcNAcylation promotes de novo nucleotide synthesis and NAD production to support tumor growth." (PMID 37308732, 2024). "The finding exhibited that PRPS1 level was observably elevated in CRC tissues and cell lines, compared to non-tumor tissues and HIEC." (PMID 34113562, 2021). "The introduction of PRPS1 WT rescued tumor growth, whereas the PRPS1 2A mutant failed to produce the same effect." (PMID 37308732, 2024). "Interestingly, even though the protein abundance of PRPS1/2 was not altered among the tumor, and tumor-adjacent tissues, the T225 phosphorylation of PRPS1 and the S41 phosphorylation of PRPS2 were enhanced in the tumor tissues." (PMID 36720864, 2023).
infection (4 papers, 2016 to 2022). The state of being infected such as from the introduction of a foreign agent such as serum, vaccine, antigenic substance or organism. "In our previous study, the PRPS1 gene was discovered as a key disease-resistance candidate gene in yellow drum, Nibea albiflora, in response to the infection of Vibrio harveyi, through genome-wide association analysis." (PMID 35742917, 2022). "Consistent with our data, other studies have also shown reduction in PRPS1-mediated nucleotide synthesis causes infections associated with leukocyte deficiencies in humans." (PMID 27425195, 2016). "We first generated stable PSCs with overexpression of PRPS1 or PRPS2 using lentivirus-mediate infection." (PMID 33493137, 2021). "Taken together, these data strongly suggest PRPS1-related nucleotide synthesis is an important factor in leukocyte homeostasis and infection prevention." (PMID 27425195, 2016).
neurological disorders (4 papers, 2014 to 2025). "Inborn mutations of PRPS1 are associated with a number of neurological disorders with a broad range of pathological symptoms." (PMID 32650483, 2020). "At the same time, it is truly difficult to determine which metabolic pathway downstream of PRPS is responsible for the pathology of PRPS1-associated neurological disorders." (PMID 32650483, 2020). "Because PRPS1 is an X-linked gene, PRPS1-associated neurological disorders, caused by either loss-of-function or gain-of-function mutations, primarily affect males." (PMID 32650483, 2020). "Importantly, prps1a;prps1b double mutants showed many features that are associated with PRPS1-associated neurological disorders such as defects in inner ear hair cells and motor neurons." (PMID 32650483, 2020). "Interestingly, PRPS1 mutations associated with neurological disorders can be either a loss-of-function or gain-of-function mutation." (PMID 32650483, 2020). "Research has shown that PRPS1 is critical not only in zebrafish but also in other species, being associated with various hereditary diseases, including NSHL and neurological disorders." (PMID 40677922, 2025). "In fact, inborn mutations in many other purine and pyrimidine genes downstream of PRPS1 also result in a variety of nervous system disorders." (PMID 32650483, 2020). "This raises the possibility that PRPS1-associated disorders may not be limited to neurological disorders." (PMID 32650483, 2020). "Although knockout mice of PRPS1 and PRPS2 have been generated, neither were designed to interrogate PRPS-associated neurological disorders." (PMID 32650483, 2020).
neurodevelopmental disorder (2 papers, 2022 to 2024). A behavioral and cognitive disorder with onset during the developmental period that involves impaired or aberrant development of intellectual, motor, or social functions. "Mutations in ANKRD11, ATP6AP2 and PRPS1 have also been associated with several neurodevelopmental disorders with ID in humans." (PMID 36551904, 2022).
myopathy (1 paper, 2021). A disease of the muscle in which the muscle fibers do not function properly. "Among these proteins, some are associated with a primarily neuromuscular disorder (TELT, HSPB8, HXK1, PRPS1) or myopathy (LDHA)." (PMID 34360601, 2021).
retinopathy (1 paper, 2025). "The final diagnosis of PRPS1-associated retinopathy and Charcot–Marie–Tooth disease type 5 was made." (PMID 40426944, 2025).
PRPS1 also shares sentences with these, for which no sentence is quoted: peripheral neuropathy (5 papers); genetic disorder (4); Hearing impairment (4); Intellectual disability (4); Cognitive impairment (3); B cell lymphoma (2); Charcot-Marie-Tooth disease type 5 (2); developmental delay (2); Optic neuropathy (2); polyneuropathy (2); Rosenberg-Chutorian syndrome (2); sensorineural hearing loss (2); severe combined immunodeficiency (2); achondroplasia (1); Alport syndrome (1); Alstrom syndrome (1); auditory neuropathy (1); B-cell acute lymphoblastic leukemia (1); Bardet-Biedl syndrome (1); Brown-Vialetto-Van Laere syndrome (1); central nervous system disorder (1); cerebellar ataxia (1); colon cancer (1); cone-rod dystrophy (1); connective tissue disorder (1); Dystonia (1); Encephalopathy (1); HGPRT deficiency (1); high blood pressure (1); Hypertension (1).
A further 15 diseases each share a sentence with PRPS1 in 1 paper.